NRG1 (neuregulin 1)
Diseases named in the same sentence as NRG1 in open-access papers (continued):
Sharing a sentence is not in itself a finding about the gene and the disease.
cancer (continued). "ARG1 expression was the most strongly associated with IL1A, NRG1, CCL1, and CRP in cancer str of the CRC tumors among the numerous associated genes (13 401 genes)." (PMID 38557819, 2024). "On the other hand, the CAFs-derived NRG1 (SE = 3.6) activation of cancer cell ERBB2 and ERBB3 receptor tyrosine kinases as a paracrine mechanism supports mutant KRAS-independent growth." (PMID 38892190, 2024). "In summary, disruption of the NRG1/ERBB4 (ALS19) axis offers therapeutic possibilities for both cancer and neurologic diseases such as ALS." (PMID 38369520, 2024). "Herein we discuss the diverse role of NRG1 in various disease types, as well as possible implications for precision targeted therapeutics in both neurologic disease and cancer, based on cross-fertilization of knowledge from each field to the other." (PMID 38369520, 2024). "CAFs develop resistance to enzalutamide or ADT via the binding of secreted neuregulin 1 (NRG1) to human epidermal growth factor receptor 3 (HER3) in cancer cells." (PMID 39092186, 2024). "Neuregulin-1 (NRG1) is an important regulator of ErbB-mediated pathways involved in cancer development." (PMID 39123493, 2024). "Dysregulation of NRG1 expression can occur through genetic alterations, epigenetic changes, or altered transcriptional regulation, leading to its involvement in cancer development and progression." (PMID 38957319, 2024). "It is essential to explore potential therapeutic strategies and efficacy predictors for NRG1 fusion-positive cancers." (PMID 37587479, 2023). "Forced NICD overexpression in LG-treated 4T1 cells increased both protein and mRNA levels of Nrg1 in cancer cells compared to that in control cells." (PMID 36707514, 2023). "Due to the low incidence of NRG1 fusions and various fusion partners, additional research is needed to further understand the biology and therapeutic strategies of NRG1 fusion-positive cancers." (PMID 37587479, 2023). "Seribantumab is a monoclonal IgG2 antibody against ErbB3, and it has also been shown to be a potentially beneficial treatment for NRG1-fusion cancers." (PMID 36909198, 2023). "In 2021, due to the initial efficacy of zenocutuzumab in clinical trials, the FDA approved zenocutuzumab for the treatment of NRG1-fusion cancers." (PMID 36909198, 2023). "Remarkably, some receptors (ERBB2, ITGA3, and ITGB6) were mainly expressed in cancer cells, and their putative ligands (NRG1 and FN1) were over-expressed in CAFs." (PMID 37879219, 2023). "Zenocutuzumab is a promising treatment option in development for patients with NRG1 fusion-positive cancers." (PMID 36341333, 2022). "Many groups have begun investigating NRG1 expression in cancer and how this correlates with therapeutic response with varied results." (PMID 35461210, 2022). "Because of the varying results in different cancer models, more investigation of NRG1 expression and cetuximab response must be completed." (PMID 35461210, 2022). "The mechanism involving NRG1 gene fusions that induce cancer is due to ErbB-mediated pathway activation leading to aberrant cell proliferation." (PMID 36120374, 2022). "They secrete paracrine factors such as tumor necrosis factor (TNF), WNT10A, platelet-derived growth factor alpha (PDGFA), and neuregulin 1 (NRG1) to sensitize sensory neurons, thereby promoting neuropathic pain associated with various cancers." (PMID 35067780, 2022). "Based on this proof-of-concept, a global multicenter Phase 1/2 clinical trial in NRG1 fusion-positive cancers has been initiated." (PMID 36341333, 2022). "The best polygenetic model included DIRC3_rs6759952, GAP43_rs13059137, NRG1_rs7834206, PROM1_rs72616195, LRP1B_rs1369535, and LOC100507065_rs11175834, tumorigenesis and cancer cell differentiation-related genes." (PMID 33805984, 2021). "Having shown that the levels of NRG1 downregulation in CAFs were sufficient to affect cancer cells, we next investigated the effect of NRG1 in CAFs." (PMID 33692466, 2021).
cancer (continued). "Further supporting this finding, expression levels of HER3 in CAFs were very low compared with expression levels in cancer cells and even lower in high-NRG1 CAFs." (PMID 33692466, 2021). "NRG1 exon 2 is the main transcription start site in normal breast epithelial cells and carcinoma cell lines." (PMID 33413557, 2021). "NRG1-induced elevated tyrosine-phosphorylation of HER3 proteins was remarkably inhibited by anti-HER3 mAbs in both cancer cell lines." (PMID 32002122, 2020). "In the last few years, several studies have detected neuregulin 1 (NRG1) fusion genes across different cancer types, particularly in invasive mucinous adenocarcinoma (IMA) of the lung and PDAC." (PMID 33115526, 2020). "Patients treated for HER2 driven cancers are frequently found to escape from HER2 targeting agents via NRG1 activation of the HER3 pathway." (PMID 32989604, 2020). "Intriguingly, several genes showing positive correlation in gene bodies have been previously linked to cancer, including MUC15, HEPACAM2, CA10, NRG1 and RAB25 (Mitra, Cheng & Mills, 2012)." (PMID 32832275, 2020). "Neuregulin 1 (NRG1) was discovered by multiple laboratories investigating cancer biology mechanisms, neuromuscular junction function and Schwann cell proliferation." (PMID 29856744, 2018). "This notion was further supported by pre-clinical observations that the paracrine secretions of various growth factors by neighboring fibroblast such as hepatocyte growth factors (HGF) and neuregulin 1 (NRG1) further promoted cancer cell resistance to TKIs." (PMID 29455663, 2018). "Previous studies reported that NRG1 exerts its effects in cancers by directly binding to ERBB3 or ERBB4 which heterodimerizes with ERBB2 and the ligand-receptor interaction, causes the phosphorylation of receptors and activation of signaling cascades." (PMID 30486894, 2018). "Ereg, Areg and Nrg1 are all ligands to members of the ErbB/HER growth factor receptor family, and all three proteins have been implicated in cancer development." (PMID 29720595, 2018). "We previously generated and characterized anti-NRG1 antibodies to explore their utility as cancer therapeutics." (PMID 29844389, 2018). "HER3 therefore plays an important role in the development and maintenance of HER2- and NRG1-driven cancers, and represents an attractive target for directed therapy." (PMID 27942917, 2017). "NRG1 signaling is involved in the development and function of several organ systems, human diseases, and cancer development." (PMID 27626312, 2016). "The effects of NRG-1 have been shown to be mediated by NF-kB signaling during tumorigenesis in cancers and axonal myelination." (PMID 27596278, 2016). "Previous studies demonstrated that NRG-1 can activate the NF-kB signaling pathway cancer cells and Schwann cells." (PMID 27596278, 2016). "Among cancer-related cytokines, Nrg1 is one of the most active members of the epidermal growth factor (EGF)-like family." (PMID 25560389, 2015). "One research group has developed a novel bispecific mAb that can sequester EGFR ligands and NRG-1, resulting in anti-proliferative effects in several cancer models." (PMID 25344208, 2014). "NRG1 also been shown to be sufficient in promoting invasion and metastasis of cancer cells, processes which are dependent on at least some of the same adhesion mechanisms." (PMID 18159252, 2007). "In NRG1 fusion-driven cancers, the aberrant fusion protein accumulates at the cell surface." (PMID 40223139, 2025). "The gene NRG1 appears to have a context-dependent function in different cancers." (PMID 41439026, 2025). "Consistent with this, a small subset of mHSPC and mCRPC showed cancer cell expression of NRG1." (PMID 40857406, 2025). "Other studies indicate that NRG-1 could be increased in cancer and neurological diseases, which makes it a pharmacological target." (PMID 40224962, 2025). "Interestingly, disruption of the NRG1/ERBB4 axis holds therapeutic potential for both cancer and ALS." (PMID 40469844, 2025).
cancer (continued). "Neuregulin 1 (NRG1) gene fusion was detected in various carcinomas." (PMID 40570725, 2025). "Although NRG1 fusions are rare in cancer, occurring in 0.15-0.5% of malignancies, they can be found in multiple types of cancer and, in addition, NRG1 may have numerous fusion partners." (PMID 38369520, 2024). "These indicated that Lnc_025370 can upregulate the expression of NRG1, suggesting that Lnc_025370 may exert a cancer-promoting effect by activating NRG1." (PMID 39727977, 2024). "According to a number of studies, cancers with high levels of NRG1 expression before antibody treatment may respond better to HER3 antibodies that do not compete with the NRG binding site." (PMID 38835349, 2024). "Furthermore, NRG1 genomic abnormalities (especially fusions, which enhance the activity of NRG1) have been found in advanced cancers." (PMID 38369520, 2024). "In the cancer realm, NRG1 genomic abnormalities (especially fusions that result in enhanced function) have been found in advanced cancers, a discovery which could be therapeutically important." (PMID 38369520, 2024). "However, most isoforms contain the same extracellular epidermal growth factor-like (EGF-like) domain, which is crucial in the case of NRG1 fusions to keep the functionality of the aberrant protein and drive cancer cell development." (PMID 39123493, 2024). "Approximately 0.15–0.5% of cancers harbor NRG1 fusions that upregulate NRG1 activity and hence that of the cognate ERBB3/ERBB4 (HER3/HER4) receptors; abrogating this activity with small molecule inhibitors/antibodies shows preliminary tissue-agnostic anti-cancer activity." (PMID 38369520, 2024). "A preclinical modeling study indicated that administering zenocutuzumab in patients with NRG1-positive cancer could lead to persistent clinical responses." (PMID 38627681, 2024). "Stromal production of NRG1 has been reported to facilitate progression in several cancers." (PMID 36357571, 2023). "Briefly, nuclear extracts of Met1 cancer cells grown under LG or HG conditions were incubated with a synthetic Nrg1 enhancer oligonucleotide tagged with biotin as bait, and binding proteins were eluted using streptavidin beads and identified using mass spectrometry." (PMID 36707514, 2023). "Likewise, zenocutuzumab, an ERBB2/ERBB3 (HER2/HER3) bispecific antibody, is under evaluation in clinical trials for patients with NRG1-positive fusions in cancer and has a 34% ORR." (PMID 37958963, 2023). "NRG1 fusion proteins are also closely related to cancer drug resistance." (PMID 36909198, 2023). "Limiting the activity of ERBB2-ERBB3 heterodimer may be the most effective strategy for NRG1 fusion-positive cancers." (PMID 37587479, 2023). "NICD was recruited to the Nrg1 enhancer region in HG-treated Met1 cancer cells." (PMID 36707514, 2023). "However, these HG-driven cell viabilities were attenuated by Nrg1 knockdown in Met1 and 4T1 cancer cells." (PMID 36707514, 2023). "Although ErbB2 and ErbB4 play an important role in NRG1-promoted cardiac repair, overexpression of ErbB2 receptor subunits can promote uncontrolled cancer growth (Wadugu and Kühn, 2012), which would be the greatest limitation of clinical interventions to achieve myocardial regeneration with ErbB2." (PMID 36120374, 2022). "In addition to ALK, RET, NTRK1, and ROS1, fusions involving FGFR1/2/3 and NRG1 genes have been reported in NSCLC among other cancers and represent emerging therapeutic targets." (PMID 35328282, 2022). "Functional downregulation of NRG1 was confirmed by using the CAF-siNRG1 CM on cancer cells." (PMID 33692466, 2021). "Similarly, migration and proliferation of cancer cells induced by CAFs CM was also diminished upon NRG1 downregulation in CAF#3." (PMID 33692466, 2021). "Indeed, NRG1-autocrine signaling has been described in a subset of human cancers, such as head and neck and melanoma, to predict sensitivity to HER2/HER3 kinase inhibition." (PMID 33692466, 2021).
cancer (continued). "Therefore, ERBB-targeted treatments, such as the monoclonal antibody zenocutuzumab and the small molecule afatinib, have been evaluated for their anticancer efficacy in patients with NRG1 fusion-positive cancers." (PMID 34068503, 2021). "NRG1 is one of four ligands (NRG 1–4) for the human epidermal growth factor receptor family (HER 1–4), which in turn is strongly implicated in the growth and spreading of cancer cells." (PMID 34288395, 2021). "NRG1 gene fusions may be clinically actionable, since cancers carrying the fusion transcripts can be sensitive to tyrosine kinase inhibitors." (PMID 33413557, 2021). "However, while normal epithelial cells produce significant amounts of NRG1 and its receptors, many cancer cell lines have reduced expression of NRG1." (PMID 34068503, 2021). "Next, we tested the ability of NRG1 in the CAF-CM to promote proliferation of cancer cells." (PMID 33692466, 2021). "NRG1 gene fusions have been identified in multiple types of cancers." (PMID 34680187, 2021). "Cancer cells may adopt various strategies, such as amplified KIT signaling, increased EGFR phosphorylation, KRAS mutations oncogene, or increased NRG1 for activating HER2/3 kinases to survive crizotinib treatments." (PMID 32164629, 2020). "We find that Neuregulin (NRG1) is a known cancer gene and is only identified by DriveWays." (PMID 33319839, 2020). "NRG-1 has been proposed as a biomarker for clinical development of HER3 antibody cancer therapies." (PMID 27582551, 2016). "In cancer cells and Schwann cells, NRG-1 signals through erbB2 and erbB3 receptors." (PMID 27596278, 2016). "Considering the role of NRG-1 in the HER3/DJ-1 interaction and activation of HER3 signaling, high DJ-1 levels in cancer may predict high HER3 signaling potential when NRG-1 level is high." (PMID 27582551, 2016). "However, NRG-1 also binds to ErbB3 on cancer cells forcing it to the “open conformation” and favoring formation of new oncogenic complexes." (PMID 27596216, 2016). "To understand the effect of NRG-1 on the association of HER3 and DJ-1, we investigated the DJ-1/HER3 association in the presence or absence of NRG-1 by co-IP and WB detection using T47-D and MCF-7 cancer cells." (PMID 27582551, 2016). "The up-regulation of αvβ3 integrin and low expression of HRG/NRG1 in cancer cells could be a novel molecular marker of chemosensitivity." (PMID 19775429, 2009). "Furthermore, the activation of AKT/mTOR signaling by NRG1 induces high expression of PDGFC in cancer cells, which in turn promotes the activation of fibroblasts and NRG1 expression through the release of PDGFC, forming a positive feedback loop between NRG1 and PDGFC." (PMID 41213930, 2025). "Moreover, there are some premises that epigenetic changes may also dysregulate the NRG1 expression, leading to its involvement in cancer development and progression." (PMID 39123493, 2024). "Thus, cancers that harbor NRG1 fusions may be treated with specific ERBB2/HER2 or ERBB3/HER3 or pan ERBB/HER pathway inhibitors." (PMID 38369520, 2024). "AREG and NRG1 expressions in cancer stroma were not closely associated with CAFGs (LRRC15, R = 0.04 and 0.03, respectively) at all, suggesting that EGFR ligands-expressed CAFs may be unique subpopulations among CAFs." (PMID 38892190, 2024). "NRG1 fusion-bearing cancers may be therapeutically important." (PMID 38369520, 2024). "The optimal methodology for screening NRG1 fusions across various cancers remains unclear." (PMID 38173003, 2024). "In addition, TPAC cancer cells overexpressed Fgf9, which promotes proliferation of neuronal precursors, Nrg1, which has been shown to drive proliferation and/or induce myelin differentiation, and Nrg4, which is involved in the establishment of early sensory innervation in the skin." (PMID 37607005, 2023).
cancer (continued). "Interestingly, high stromal NRG1 expression correlated with significantly higher disease-specific survival, whereas the NRG1 expression level in cancer cells did not associate with survival differences." (PMID 36912192, 2023). "Hence, identifying predictive factors for ERBB targeted therapy in NRG1 fusion cancers may help to guide clinical decision." (PMID 37587479, 2023). "Therefore, anti-NRG1 may represent a new method for targeting the pancreatic matrix and cancer cells." (PMID 34692670, 2021). "Cytokines such as TNF, growth factors including PDGFA and NRG1, and others like WNT10A were identified to interact with their receptors on neurons or other cells such as microglial cells to directly or indirectly sensitize neuropathic pain associated with cancers." (PMID 32434423, 2020). "The description of the multiple modes of action of the anti-HER3 antibody 9F7-F11 not only adds to our basic understanding of dysregulated signaling in cancer, but might help the selection of drug combinations and clinical indications for 9F7-F11 in NRG1-addicted or NRG1-rearranged cancer." (PMID 31443721, 2019). "However, NRG-1 may be a growth factor for cancer cells, and further studies are necessary to assess the safety and efficacy of NRG-1 in HF." (PMID 29563880, 2018). "Neuregulin-1β (NRG1) has been studied as a cardioprotective factor, yet its mechanisms during DOX treatment, particularly in the presence of cancer, are not well understood." (PMID 42196592, 2026). "In turn, cancer cell-derived PDGFC promotes fibroblast activation and high NRG1 expression, forming a positive feedback loop between NRG1 and PDGFC." (PMID 41213930, 2025). "Although we showed upregulated NRG1 and FGF2 level in the cancer cells (DTP cells), it is possible that CAFs and other types of cells actively provide ERBB family and FGFR family ligands." (PMID 39369284, 2025). "The overexpression of NRG1 can activate the ERBB3/ERBB2-signaling pathway, promoting cancer cell proliferation, invasion, and metastasis." (PMID 41378303, 2025). "In this study, we find that two ERBB receptor ligands are transcriptionally upregulated by CAFs after endocrine treatment (NRG1 and HBEGF) and contribute to cancer cell endocrine therapy resistance." (PMID 40341770, 2025). "Recently, there have been several studies analyzing NRG-1 gene fusions engaged in altering the dimerization of HER family proteins and the consecutive results of their activation in different types of cancer." (PMID 39123493, 2024). "Increased NRG1 expression can activate downstream signaling pathways, such as the ERBB2/ERBB3 pathway, which promotes cancer cell proliferation, migration, and survival." (PMID 38957319, 2024). "Thus, the NRG1 fusions may be considered as biomarkers in various cancer types." (PMID 39123493, 2024). "Neuregulin-1 (NRG1), a member of the NRG gene family, has emerged as a key player in tumorigenesis and cancer progression." (PMID 38957319, 2024). "At the mRNA level, the expression of Nrg1 and Notch target genes decreased following DAPT treatment in HG-treated cancer cells." (PMID 36707514, 2023). "To ascertain the specific receptor and cell type through which NRG1 acts to promote invasion, we performed an RNAi screen of all four ERBB receptors (ERBB1-4) in both the cancer cell and PSC compartments of our sphere model." (PMID 36357571, 2023). "By the binding to HER3 ligands, like neuregulin 1 (NRG1), HER3 plays important roles, such as in the differentiation and proliferation of normal and cancer cells." (PMID 36751113, 2023). "Upon binding to neuregulin 1 (NRG1), ERBB3 preferentially dimerizes with HER2 (ERBB2), in turn inducing aggressive features in several cancer types." (PMID 35406375, 2022). "NRG1/HER3‐activated signalling pathways (e.g. PI3K‐AKT) promote cell proliferation, migration and survival, while blocking of NRG1‐mediated HER3 activation inhibits migration and growth of cancer cells in preclinical models." (PMID 34288395, 2021).